CCL2 (C-C motif chemokine ligand 2)
Diseases named in the same sentence as CCL2 in open-access papers (continued):
Sharing a sentence is not in itself a finding about the gene and the disease.
infection (continued). "The mRNA expression of various inflammatory cytokines (Il-6, Tnf-α, Ifn-γ, and Ifn-β) and chemokines (Ccl2, Ccl4, Ccl12, Cxcl1, and Cxcl10), but not Il-1β, was elevated in the lungs at 2 dpi, in the early stage of infection." (PMID 34463644, 2021). "On the other hand, we noted increased levels of monocyte/macrophage associated chemokines CCL2/MCP1 and CCL4/MIP1β in rAd5-YFV vaccine-immunized mice that were not seen in controls in response to CO92 infection." (PMID 33514747, 2021). "Moreover, macrophages presented the earliest and strongest transcriptional response to the infection, primarily responding to intracellular viral RNA with pro-inflammatory cytokines such as CXCL10, CCL2, and others." (PMID 34381043, 2021). "Moreover, data showed that LP17 not only abrogated the significant difference in IL1β and TNFα expression, but also eliminated the apparent difference in CCL2 and CXCL10 expression between both groups of S. typhimurium-infected mice at 3 days post-infection." (PMID 33475464, 2021). "Despite different approaches, the exact roles played by CCL2 and CCL7 in recruitment of monocytes are unclear; however, we do know that lack of expression leads to a significant reduction in monocyte numbers during infection." (PMID 33829283, 2021). "Monocyte chemoattractant protein-1 (MCP-1) or CCL2: It is a signaling molecule secreted by monocytes, memory T cells, and recruiting other immune cells to the sites of inflammation and infection." (PMID 33573064, 2021). "In the early stages of the infection, a group of cytokines and pro-inflammatory chemokines are expressed including interleukin-1β (IL-1β), IL-2, IL-6, interleukin-8 (IL-8), both IFN-α/β, tumor necrosis factor (TNFα), CCL, CCL3, CCL5, CCL2, and IP-10." (PMID 34220861, 2021). "Phototherapy failed to change CCL2 levels in the plasma of euthanized animals after 9 days of infection." (PMID 34722326, 2021). "Surprisingly, mice that were deficient in MCP-1/CCL2, MCP-3/CCL7, and MCP-5/CCL12, individually or collectively, were not nearly as susceptible to ID LVS infection as CCR2 KO mice." (PMID 33760886, 2021). "Monocyte chemotactic protein 1 (MCP1 or CCL2), macrophage inflammatory protein 1 (MIP-1α or CCL3), and MIP-1β (CCL4) are crucial for macrophage migration/invasion and immune responses toward infection and inflammation." (PMID 33748112, 2021). "Infection of female mice with M. circinelloides but not males resulted in increased levels of CCL2, CCL3 and CCL4." (PMID 33919611, 2021). "As infection progressed in the vehicle controls, increased amounts of IL-6 and TNF-α, along with chemokines responsible for monocyte and neutrophil recruitment (CCL2, MIP-2a, and CCL4), were detected in the serum, and this pattern of inflammation was mirrored in the lungs." (PMID 34835277, 2021). "We detected, however, a significantly enhanced transcriptional induction of plant defense genes in CCL2- but not CCL2-Y92A-expressing lines in response to infection with B. cinerea compared to WT plants." (PMID 33897746, 2021). "Nonetheless, at this LVS infection dose, mice lacking circulating MCP-1/CCL2, MCP-3/CCL7, and MCP-5/CCL12 largely survived, while CCR2 KO mice did not." (PMID 33760886, 2021). "Furthermore, the top six DEGs, including CSF3, CCL2, CCL7, IL6, CXCL11, and CXCL10, were all upregulated after infection at P3." (PMID 34026883, 2021). "Similarly, IDO1 showed sixfolds increase, whereas LIF, IL6, CCL2, and VEGF each showed more than threefold increase in expression post infection." (PMID 32546788, 2020). "At the site of infection, infected cells produce chemokines and cytokines such as type I IFNs, IL-6, IL-8, TNF-α, CCL2 (MCP-1), RANTES, and MIP-1α that recruit immune cells including NK cells, neutrophils, macrophages and DCs to the site of infection where they initiate the innate immune response." (PMID 32375274, 2020). "Both CCL2 and CXCL1 were upregulated rapidly upon infection of liver tissue." (PMID 32651360, 2020).
infection (continued). "Monocyte chemoattractant protein 1 (MCP-1), also known as chemokine ligand 2 (CCL2), is involved in the recruitment of macrophages to infection sites within the central nervous system (CNS), and preclinical studies have demonstrated a relationship between MCP-1 and the kynurenine pathway." (PMID 31302732, 2020). "Deficient adaptive immunity in the periphery is likely influencing the NP response to infection, as several inflammatory cytokines and chemokines were higher at onset and/or sustained longer in sOP children during AOM pathogenesis, including CCL2, IL-12, IL-17A, and TNF-a." (PMID 32595639, 2020). "MCP-1, also called chemokine (C-C motif) ligand 2 (CCL2), is a pain-related inflammatory cytokine that recruits several types of immune cells to the sites of inflammation in the condition of tissue injury or infection." (PMID 32811461, 2020). "The genes, Ccl2, Ccl20, Csf1, Cx3cl1, Cxcl1, Cxcl3, Il6, Birc3, Map3k8, Nos2, Nfkb2, Tnfrsf1b, and Vcam1, played core roles in a PPI network, and interacted closely with other ones in the infection." (PMID 33042984, 2020). "Melatonin treatment (30 nM) reduced the levels of IL-6 (2-fold), MCP-1/CCL2 (5-fold), and RANTES/CCL5 (6-fold) compared to vehicle treatment after both 4 and 24 h of infection, while both vehicle and melatonin treatment reduced the levels of IL-10, MIP-2/CXCL2, and KC/CXCL1." (PMID 30949455, 2019). "Infection of human cortical collecting duct epithelial cells with BKPyV resulted in downregulation of TNFα expression, but upregulation of the TNF receptors 1 and 2, TLR3, RIG-1, IL-6, IL-8/CXC8, CCL5/RANTES, CCL2/MCP-1, and CXCL10/IP-10." (PMID 31408949, 2019). "Therefore, we analyzed control and TIM-1-/- organs following EBOV GPΔO/rVSV infection for the chemokines, CXCL10 (IP-10) and CCL2 (MCP-1)." (PMID 31242184, 2019). "The cytokine CCL2 (previously known as MCP-1) is a chemokine that is primarily responsible for inducing and regulating the migration and infiltration of macrophages to the sites of inflammation produced by either tissue injury or infection." (PMID 31316998, 2019). "Infection triggered similar cytokine storms in both genotypes as illustrated by the equivalent large quantities found in the bloodstream of Ripk1LPC-KO and Ripk1fl/fl mice, such as for TNF-α, IL-6, and CCL2." (PMID 30622241, 2019). "In contrast to these findings, infection with the hRSV Long strain in NHBEs cells did not lead to the secretion of CCL2 and CCL3, but the levels of CCL5 were increased as compared to uninfected cells." (PMID 30936869, 2019). "Levels of TNF-α and CCL2 were significantly elevated from pre-clinical to early-stage infection, and IL-6, IL-12b, CCL3, CCL12, and ISG15 levels were significantly elevated from pre-clinical to late-stage infection." (PMID 31790513, 2019). "After 6 h of infection, the production of IL-6, CXCL1, and CCL2 increased in WT PMCs, but not in Tlr2-deficient PMCs (P < 0.001, for each at MOIs of 0.05 and 0.1)." (PMID 31636643, 2019). "Overall, these findings suggest that CCL2 may represent a key factor enhancing HIV spreading, particularly in anatomical sites where infection of macrophages plays a prevalent role." (PMID 31377844, 2019). "In fact, results from a recent study demonstrated that peripheral infection with WNV increased CNS expression of chemokines important for lymphocyte trafficking, including CCL2, CCL7, CXCL9, and CXCL10, in PLX5622-treated mice compared with control-treated mice." (PMID 30704498, 2019). "The CCL2/MCP-1 has its role in macrophage and monocyte recruitments to the site of infection." (PMID 30744623, 2019). "On the 28th day of infection and 23 days of treatment, the euthanasia occurred, and the heart preserved for histopathological, oxidative stress (SOD, catalase, TBARs, carbonylated proteins) and plasma (CCL2, CCL5, TNF, IL-10) analyses." (PMID 30365644, 2018). "CXCL1, CCL2, and CCL7 in the lungs were significantly increased in aged mice after infection." (PMID 30018181, 2018).
infection (continued). "We found a significant increase in MCP-1 (C-C Motif Chemokine Ligand 2 (CCL2), a key chemokine that regulates migration and infiltration of monocytes/macrophages to the site of infection) in TB/Flu co-infected compared to TB only patients following overnight stimulation of whole blood with PPD." (PMID 30662443, 2018). "Finally, among the elevated serum cytokine levels for the acute phase of infection, many were monocyte chemoattractants or secreted by monocytes and macrophages (e.g., CXCL10, CCL2, and IL‐10)." (PMID 30150281, 2018). "Severe IV infection induces many cytokines; IFNαβ, TNFα, IFNγ, C-X-C motif chemokine (CXCL) 10 (CXCL10), CXCL9, C-C motif ligand (CCL) 2 (CCL2), CCL4, CCL5 and interleukin (IL)−6 (IL-6), IL-2, IL-8, and IL-10 have all be observed to be upregulated during severe IV infection in humans." (PMID 30250466, 2018). "Similar to airway epithelial cells, human macrophages express type I and type III IFNs, IL-1α, IL-1β, IL-6, TNF-α, CXCL8, CCL2 (MCP-1), CCL3 (MIP-1α), CCL4 (MIP1-β), CXCL9, and CXCL10 following infection with seasonal H1N1 or with H5N1, 2009 H1N1 strains demonstrating increased pathogenicity." (PMID 29623073, 2018). "By contrast, pathogens cause epithelial cells to release proinflammatory factors, such as IL-8 (CXCL-8), MCP-1 (CCL2) and MIP-3α and might trigger rapid response to clear the infection." (PMID 29896198, 2018). "Thus, CCL2, MIP‐2 and KC mRNA levels were clearly lower in the kidney of p38γ/δ−/− and LysM‐p38γ/δ−/− mice than in WT animals at day 1 post‐infection." (PMID 29661910, 2018). "Regarding the chemokines, diverse studies in humans and mice have indicated that CXCL1, CXCL9, CXCL10, CCL2, CCL3, CCL4, and CCL5 are important in controlling the infection during the acute phase, and the levels of virtually all of them were increased in both BALB/c and C57BL/6 mice." (PMID 29662478, 2018). "Expression of viral RNA, as well as Ccl5 and Cxcl10, but not Tnfα, Il6 Ccl2, Ifna and Ifnb, was significantly decreased in the footpads of Bclx+/- mice at 5 days post-infection." (PMID 30261081, 2018). "In particular, CCL2, CXCL5, and CXCL10 had increased levels early after wounding and infection." (PMID 30138446, 2018). "Transfection experiments with CedPV P protein demonstrated that the IFN response in HEK293T or HeLa-CCL2 cells was less antagonized when to compared to IFN signaling antagonism with HeV P protein and infection with wild-type CedPV stimulated the IFN-β response in infected HeLa-CCL2 cells." (PMID 29587789, 2018). "At lower infection doses, significant differences in height and kinetics of cytokine concentrations in BAL-f were mostly confined to the time point around the maximum cytokine response (2–4 h for IL-1β and Ccl3, 2–8 h for TNF, 8–24 h for Cxcl-1, Ccl2)." (PMID 29734720, 2018). "In addition, the viral titer in CCL2-null mice, and the effects of anti-CCL2 therapy of wild-type mice subjected to H7N9 infection, warrant further investigation." (PMID 28421067, 2017). "The network analysis revealed a strong correlation between IL-6 and MCP-1/CCL2, regardless of parasite load, suggesting that these mediators were induced by the infection itself." (PMID 28118834, 2017). "CCL2 is significantly up-regulated during H1N1, H5N1, and H7N9 infections." (PMID 28421067, 2017). "Following infection, expression levels of the immunomodulatory cytokines C-C motif chemokine 22 (CCL22), CCL1, IL-23α, IL-3, IL-4, matrix metalloproteinase 9 (MMP9), IL-21, C-X-C motif chemokine 2 (CXCL2), and CCL2 were increased." (PMID 28507072, 2017). "As determined by ELISA analyses, HSV-2 WT infection strongly enhanced the production of TNF-α, IL-6, IL-8 and CCL2, but the levels of these proinflammatory cytokines and chemokines were inhibited in End1/E6E7 cells which were infected with the Us2 mutant of HSV-2." (PMID 28827540, 2017).
infection (continued). "C-C motif chemokine ligand 2 (CCL2), also known as monocyte chemoattractant protein (MCP)-1, binds to the chemokine receptors CCR2 and CCR5, and is an important regulator of monocyte/macrophage trafficking during infection or in the presence of inflammation." (PMID 28421067, 2017). "The genes with strongest induction included chemokines (e.g. CXCL11, 84-fold; CXCL10, 18-fold; CXCL9, 9-fold; CCL2, 9-fold) and cytokines (e.g. IL6, 54-fold; IL12B, 10-fold; IL1B, 9-fold;) etc. consistent with the infection of host phagocytes with Mtb reported earlier by us." (PMID 28880895, 2017). "In our analysis, we observe that a subset of these cytokines reported to be present in the serum also show transcriptional upregulations in PBMCs by 4 days post-infection (IL6, IL1B, IL1RN, CCL8, CXCL10) and by 7 days post-infection (CCL2, CCL3, CSF1, TNF, CXCL1, FAS and CXCL8)." (PMID 27595844, 2016). "The molecules that depicted significant increases in those mAb treated-mice at 96 h after infection were CXCL1 (KC), CCL2 (MCP-1), CCL3 (MIP-1α), CCL4 (MIP-1β), CXCL2 (MIP-2), CXCL5 (LIX), IL-1α, IL-6, G-CSF, M-CSF, and TNF-α (for all, P < 0.01) and IL-1β, IL-15, IL-10, and LIF (for all, P < 0.05)." (PMID 27642235, 2016). "On the other hand, PRRSV could inhibit IFN-mediated JAK-STAT signaling pathways to interrupt ISG transcription; for example, ISG15, ISG56, CCL2, MX1, OAS2, and RNaseL of PAMs were significantly downregulated after infection with the PRRSV strain VR2385." (PMID 27182980, 2016). "The fact that the CCL2 transgenic animals without S. pneumonia infection did not developed OP, points to the importance of the infections in the disease’s development." (PMID 27282780, 2016). "The role of CCL2 in inducing Th1 protective immunity and fungal clearance during C. neoformans infection has been demonstrated by its involvement in recruiting macrophages, CD4+ T cells, and NK T cells to the site of infection." (PMID 27165801, 2016). "In agreement with the elevated levels of recruited monocytes and macrophages at day 8 post-infection in control A20WT mice, higher levels of CCL2 could be detected in BAL fluid of these mice compared to A20AEC-KO littermates at this stage." (PMID 26815999, 2016). "Levels of IL-1β, IL-6, CCL2, CCL3 and CCL5, which are known to play an important role during HSE, were measured in brain homogenates using magnetic bead-based immunoassays prior to (day 0) and on days 6, 8 and 10 following infection." (PMID 27930721, 2016). "To assess the importance of reduced CCL2 levels in A20AEC-KO mice for their protective phenotype upon influenza virus infection, we administered recombinant mouse CCL2 (rCCL2) to A20AEC-KO mice at day 6 post-infection." (PMID 26815999, 2016). "Through induction of IL-6 as well as chemokines such as CCL2, CXCL8, and CXCL10, Vγ9/Vδ2 T cells and MAIT cells are likely to enhance local inflammation and contribute to further recruitment of monocytes, neutrophils, and lymphocytes to the site of infection." (PMID 27527598, 2016). "As hypothesized, the levels of inflammatory mediators (IL-6, CCL2, CCL3, CXCL1, CXCL10 and IFNα as expected) were lower in the blood and the spleen of Ifnar1-/- mice compared to WT counterparts at all times post-infection, except for IFNγ." (PMID 27792766, 2016). "Despite this variability, treatment of MDM with anti-CCL2 Ab led to a significant decrease in the accumulation of HIV-1 DNA copies at both time points, with a more profound reduction of viral DNA levels at 7 days post-infection." (PMID 25608886, 2015). "MDM exposed for 20 h to anti-CCL2 or control Ab were infected with HIV-1BaL either in the absence or in the presence of dNTPs, and the percentage of p24 Gag+ cells was assessed 14 days post-infection." (PMID 25608886, 2015). "Therefore, MDM exposed for 20 h to anti-CCL2 or control Ab were infected with HIV-1BaL and A3A expression was analyzed 14 days post-infection by Western blot analysis." (PMID 25608886, 2015).
infection (continued). "Using cells only treated with IL-33 or cells only infected with HTNV as controls, the mRNA expression of IL-1β, IL-6, IL-8, CCL2, CCL20, CXCL1, CXCL2, and CX3CL1 was significantly induced in HUVECs prior to infection with HTNV (MOI = 1) for 48 h and then exposed to IL-33 (20 ng/ml) for 6 h." (PMID 25658420, 2015). "Results indicate that the presence of anti-CCL2 Ab did not influence HIV-1 DNA synthesis in the infected cells early post-infection." (PMID 25608886, 2015). "CCL2 (also known as MCP-1) is essential for the cellular response in M. tuberculosis infection, recruiting leukocytes (in particular, monocytes, and T-lymphocytes) to the sites of infection or injury." (PMID 26041993, 2015). "Neutrophils that are primarily recruited by CXCL8 can exert antiviral immunity amongst others by the release of inflammatory cytokines (e.g., IL-12, TNFα) and chemokines (e.g., CCL2, CXCL8, CXCL9, CXCL10) that leads to further recruitment of immune cells to the site of infection." (PMID 24646914, 2014). "First, PRRSv infection resulted in a significantly increased CCL2 response to PMA/Iono stimulation on D2 and D6 but not on D19 (early induction)." (PMID 25479904, 2014). "CCL2 (MCP-1; monocyte chemotactic protein-1) is involved in recruitment of monocytes, T cells, and dendritic cells to areas of inflammation induced by tissue injury or infection." (PMID 25505466, 2014). "Consistent with the trend of NF-κB activity, the expression levels of three of the four selected chemokines regulated by NF-κB (Ccl2, Ccl3, Ccl5, but not Cxcl1), peaked on day 32 post-infection." (PMID 25116007, 2014). "However, M2-related chemokines CCL2, CCL17, and CCL22 progressively increased during the period of 13 weeks infection." (PMID 24666892, 2014). "The infection of MP with rNP LASV led to a robust and significant increase in the synthesis of CCL2, 4, 5, and 7, and of CXCL9, 10, and 11 mRNA and to a strong release of these chemokines in the culture supernatants, as shown by comparison with mock-infected cells." (PMID 24421914, 2014). "Interestingly, RPL31 and IL8 were almost exclusively expressed after Lena infection, while other genes, including CCL2 and ACADVL, were differentially regulated by infection with both strains, although to different extents." (PMID 24643046, 2014). "The infection of DC with LASV or MOPV did not lead to synthesis of the CCL2, 3, 4, 5, 7, 13, and 17 mRNAs (data not shown), whereas an increase in the levels of the mRNAs encoding CXCL9, 10, and 11 was observed in MOPV-infected DC, but not in LASV-infected DC." (PMID 24421914, 2014). "Importantly, vNA-Δ infection only induced low level of type I interferons and chemokines CXCL1/KC and CCL2/MCP-1 in epithelial cells, leading to a reduced influx of leukocytes and pulmonary injury." (PMID 24927156, 2014). "The CCL2-mediated increase in transmigration of HIV infected monocytes was not dependent on the extent of viral replication and occurred even at very low levels of infection." (PMID 23922698, 2013). "CCL2 and CXCL10 are chemokines that are low molecular weight molecules and play a pivotal role in the orchestration of an effective antiviral immune response, partly by attracting leukocytes to the site of inflammation or infection." (PMID 23637938, 2013). "However, previous studies in human and mouse monocytes/macrophages, as well as in mice, have shown that, compared to HN878, infection with CDC1551 induces higher production of inflammatory molecules, including TNF-α and CCL-2." (PMID 23958185, 2013). "The levels of suPAR were similar in the supernatants of uninfected and infected tissues during the first 6 days of infection, but raised in infected cultures 9 and 12 days post-infection, in coincidence with virus replication and increased CCL2/MCP-1 secretion." (PMID 23923008, 2013).